AGRP (agouti related neuropeptide)
Diseases named in the same sentence as AGRP in open-access papers (continued):
Sharing a sentence is not in itself a finding about the gene and the disease.
Obesity (continued). "Ubiquitous overexpression of AGRP has been shown to increase appetite, resulting in increased weight and obesity in mice." (PMID 36472402, 2023). "STAT3 ablation in AgRP neurons leads to obesity, hyperleptinemia, mild hyperphagia, and reduced responsiveness to leptin." (PMID 37887286, 2023). "AgRP neuron-specific deletions of SK3 channels resulted in a transient obesity in NCD-fed mice, but profoundly exacerbated HFD-induced obesity." (PMID 37594983, 2023). "In contrast, AgRP-specific leptin receptor deletion in adult animals leads to massive obesity, reproducing the phenotype of db/db mice." (PMID 37887286, 2023). "At the same time, ARC activates or inhibits neuropeptide Y (NPY) and agouti-related protein (AgRP) to control feeding behavior and energy metabolism, which is closely related to the onset of obesity and type 2 diabetes." (PMID 35525962, 2022). "The present review explored the molecular and physiological adaptations of leptin, insulin, POMC, and AgRP neuropeptides to IF protocols, mostly performed in animal obesity models." (PMID 35445066, 2022). "The KK-Ay mouse model with ectopic expression of the Agouti-related protein (AgRP) is hyperphagic and develops severe obesity." (PMID 35422689, 2022). "We also found that AGRP neuron–specific TET3 knockdown caused hyperphagia, obesity, and diabetes in both female and male mice, highlighting a central role of TET3 in regulating feeding, body weight, and glucose metabolism by AGRP neurons." (PMID 36189793, 2022). "Evidence in a recent report shows that the inactivation of AgRP neurons induces the browning of WAT and prevents diet-induced obesity and insulin resistance in mice, demonstrating the importance of AgRP neurons in body temperature regulation." (PMID 35301430, 2022). "By contrast, inhibition of Mfn-1 and 2 in AgRP neurons in the hypothalamus prevented diet-induced obesity in rodents fed an HFD." (PMID 33227495, 2021). "Together, we suggest that this AgRP neural circuit plays a unique role in persistent control of energy expenditure and body weight, hinting next-generation therapeutic approaches for obesity and metabolic disorders." (PMID 34112797, 2021). "Here we describe the in vivo dynamics of hunger-promoting AgRP neurons during the development of diet-induced obesity in mice." (PMID 32720646, 2020). "In contrast, nothing is known about how diet-induced obesity alters the response of AgRP neurons to sensory cues signaling food availability or their modulation by gastrointestinal nutrients during a meal." (PMID 32720646, 2020). "To understand the functional significance of these changes in AgRP neuron dynamics, we also measured the behavioral response to optogenetic manipulation of AgRP neurons before and after the development of obesity." (PMID 32720646, 2020). "Overall, we find that HFD triggers changes in AgRP neuron regulation that would be predicted to both promote and suppress obesity." (PMID 32720646, 2020). "To address this basic question, we set out to monitor and manipulate the activity of AgRP neurons in vivo in mice during the development of obesity induced by a high-fat diet (HFD)." (PMID 32720646, 2020). "We have shown that obesity broadly desensitizes AgRP neurons to an array of nutritionally relevant stimuli and further alters the ability of AgRP neuron stimulation to drive feeding." (PMID 32720646, 2020). "One interpretation of this result is that diet-induced obesity reduces the sensitivity of the downstream circuitry to AgRP neuron activity, such that supraphysiologic stimulation (i.e. concurrent stimulation) is now required to fully drive feeding." (PMID 32720646, 2020). "Ingestion of fat is communicated to AgRP neurons in part through CCK and, consistent with this, we found that obesity also desensitizes AgRP neurons to peripheral CCK." (PMID 32720646, 2020). "A critical unanswered question regards how obesity alters AgRP neuron activity in response to these diverse signals." (PMID 32720646, 2020).
Obesity (continued). "We also found that obesity blunts the rapid inhibition of AgRP neurons that occurs when hungry mice see and smell food." (PMID 32720646, 2020). "Most notably we found that obesity blunted the activation of AgRP neurons by the appetite promoting hormone ghrelin." (PMID 32720646, 2020). "In addition to advancing our understanding of the thermoregulatory system, insights into the neurocircuitry linking thermoregulation to AgRP neuron activity may help to identify novel strategies for obesity treatment by blunting the associated hyperphagic response." (PMID 33320088, 2020). "Conversely, blockade of MC4R by the agouti-related protein (AgRP) increases feeding, and complete loss of MC3R or MC4R in mice is associated with increased food intake and concomitant obesity." (PMID 32109250, 2020). "It has been reported that exposure to HFD-induced obesity can cause dysregulation of the expression of NPY and AgRP in the hypothalamus." (PMID 32585823, 2020). "We equipped mice for optogenetic stimulation of AgRP neurons and then tested them, before and after the development of obesity, using two complementary stimulation protocols." (PMID 32720646, 2020). "A murine model of corticosterone treatment resulted in increased hypothalamic expression of the melanocortin antagonist AgRP in parallel with obesity and hyperglycemia." (PMID 30794724, 2019). "In the zebrafish a genetic model of obesity has been developed by overexpressing AgRP [Tg(b-actin:AgRP)]." (PMID 30177968, 2018). "Mouse models of obesity already suggest an involvement of AGRP in growth regulation through interaction with the melanocortin system especially the MC4R." (PMID 29843787, 2018). "Several studies aimed at finding novel approaches for the management of obesity have focused on the critical role of AgRP neurons in the regulation of appetite, reporting that their direct activation rapidly increases food intake." (PMID 29619754, 2018). "Further, conditional deletion of Rb1 in POMC neurons resulted in cell cycle reentry, neuronal apoptosis, and obesity; however, in contrast, deleting Rb1 in the antagonizing AgRP/NPY neurons was well tolerated." (PMID 30185666, 2018). "Overexpression of AGRP in the mouse results in obesity and targeted inactivation of the MC4R causes obesity with features similar to the agouti obesity syndrome." (PMID 29843787, 2018). "The treatment of obesity with EA, which was employed to reduce methylation Tsc1 and inhibit the activity of mTORC1, thereby controlling appetite-regulating factors (e.g., NPY, AgRP, and PoMC) and mitigating obesity." (PMID 29853949, 2018). "Meanwhile, the genetic deletion of POMC alone is sufficient to produce massive obesity in mice, which is phenocopied in mice harboring the dual deletion of AgRP and POMC." (PMID 30185666, 2018). "Transgenic overexpression of AGRP itself in zebrafish led to both obesity and increased linear growth, while suppression of AGRP expression reduced larval growth rate and was mediated through the MC4R." (PMID 28450851, 2017).
Obesity (continued). "For instance, recent publications identified the purinergic-receptor 6 (P2Y6) as novel regulator of AgRP neuron activity and further revealed that selectively abrogating P2Y6 signalling in AgRP neurons alleviates obesity-associated insulin resistance." (PMID 28469281, 2017). "One study has shown that deletion of MFN1 or MNF2 in AgRP/NPY neurons protects mice from high-fat diet-induced obesity." (PMID 28592656, 2017). "As leptin imposes an overall inhibitory action on VTA LepR neurons, resistance to diet-induced obesity by VMAT2 deletion is in line with a general role of leptin-inhibited neurons such as AgRP neurons." (PMID 28560316, 2017). "These appetite-related factors (i.e. ghrelin, leptin, AgRP and neuropeptide Y) have been reported to moderate overeating/obesity, affecting the anticipation, consumption, and acquisition of food." (PMID 26754043, 2016). "Selective inhibition of PKA activity in AgRP neurons partially recapitulates the leanness and resistance to diet-induced obesity of RIIβ KO mice." (PMID 26381935, 2015). "Activation of POMC neurons during caloric intake protects against diet-induced obesity whereas activation of AgRP neurons informs the body to store energy during fasting." (PMID 26441839, 2015). "Central administration of NPY or overexpression of AgRP increased food consumption leading to obesity." (PMID 23543912, 2013). "Introcerebroventricular injection of AgRP or its expression in a transgenic mouse model both lead to hyperphagia, lowered energy expenditure, and obesity." (PMID 23346045, 2012). "With this in mind, modulating the activity of AgRP neurons represents one strategy to control appetite in contexts of the current obesity epidemic." (PMID 23346045, 2012). "We determined the complete sequence of the AGRP gene and upstream promoter region in 95 patients with severe obesity (BMI > 35 kg/m2)." (PMID 19602223, 2009). "Both ICV injection and transgenic overexpression of AGRP leads to increased food consumption and obesity in mice." (PMID 19602223, 2009). "Inversely, AgRP/NPY neurons seem to be affected at weaning by different models of maternal obesity." (PMID 40474775, 2025). "Notably, studies demonstrate that disrupting TET3, a key epigenetic regulator involved in DNA demethylation, activates AgRP neurons and triggers adverse metabolic effects such as binge eating, obesity, and diabetes." (PMID 40452923, 2025). "In rats that experienced caloric restriction following HFD-induced obesity, reduced repressive histone 3 lysine 9 methylation (H3K9me2) at the promoter of AgRP led to increased AgRP expression and heightened hunger signaling, suggesting anxadaptive response to restore energy homeostasis." (PMID 41040868, 2025). "Similarly, maternal diabetes and obesity also induce hypothalamic changes that result in an imbalance in AgRP/NPY and POMC expression during adulthood." (PMID 40474775, 2025). "We then sought to investigate whether the ‘obese-like’ AgRP calcium dynamics in BFDdev mice will be further affected by HFDlard-induced obesity." (PMID 41326798, 2025). "Our results indicate that the detrimental effects of obesity on sperm RNA composition may be partially mediated via a common upstream regulatory mechanism involving AgRP neurons." (PMID 40021730, 2025). "Lastly, we interrogated whether obesity affects the effects of the coordinated reciprocal interplay between AgRP and POMC neurocircuits in the regulation of feeding and metabolism." (PMID 38378998, 2024). "Under normal conditions, hypothalamic reactive oxygen species (ROS) function to maintain energy homeostasis through balancing the activation between POMC and NPY/AgRP neurons, but excessive ROS would damage these hypothalamic neurons, resulting in disturbed energy homeostasis and obesity." (PMID 38397850, 2024).
Obesity (continued). "In addition, we documented that CRISPR-mediated genetic ablation of Tet3 specifically in AgRP neurons in the mouse hypothalamus induced hyperphagia, systemic insulin resistance, obesity and type 2 diabetes." (PMID 38216792, 2024). "For example, the overexpressing AgRP (Tg(b-actin:AgRP) was used to develop a transgenic zebrafish obesity model that demonstrated the phenotype of obesity in mammals such as body weight increase, linear growth, visceral adipose accumulation, and increase total triglycerides." (PMID 38203409, 2023). "Moreover, these can be readily combined with germline alterations in genes such as AGRP, a key member of the most frequently altered pathway seen in patients with obesity, or with dietary changes such as HFDs." (PMID 36472402, 2023). "Animal models with a gain of function of orexigenic AgRP neurons develop obesity, while those with loss of function have no impact on body weight." (PMID 37069175, 2023). "We propose that the action of KDM4D through the demethylation of H3K9 is critical in maintaining a stable epigenetic landscape of the AgRP promoter, and may offer a target to develop new treatments for obesity." (PMID 36817590, 2023). "AGRP neuron–specific TET3 knockdown causes hyperphagia, obesity, and diabetes." (PMID 36189793, 2022). "Additionally, single-cell RNA sequencing of the hypothalamic ARC after HFD-induced obesity demonstrated selective changes in AgRP neurons via neuron-astrocyte interactions, which contributed to the exaggerated sympathoexcitation observed in obese rats." (PMID 34840970, 2021). "Mechanisms mediating hyperphagia and obesity in this model involve antagonism of the melanocortin receptor, and similar phenotypes have been described in mice overexpressing Agouti-Related protein (AGRP), a potent antagonist of the melanocortin receptors-3 and -4." (PMID 34604220, 2021). "Interestingly, over-expression of AGRP or administration of exogenous AGRP stimulates feeding, leading to obesity." (PMID 33716796, 2021). "Finally, our study provides a potential explanation for recent findings of AgRP neuron regulation in obesity." (PMID 34931084, 2021). "Transgenic mice over-expressing AgRP show increased obesity, food intake, and hyperinsulinemia." (PMID 32987823, 2020). "The intracerebroventricular (icv) or intraperitoneal (ip) injection of MC4R agonists can decrease food intake in goldfish, zebrafish, and coho salmon, while transgenic zebrafish over-expressing AgRP display obesity, increased linear growth, and adipocyte hypotrophy." (PMID 32987823, 2020). "Diet-induced obesity attenuates AgRP neural and behavioral responses to CCK and ghrelin." (PMID 32720646, 2020). "This indicates that obesity induced by HFD selectively desensitizes AgRP neurons to dietary fat." (PMID 32720646, 2020). "Thus, diet-induced obesity reversibly blunts the rapid inhibition of AgRP neurons in response to exterosensory cues." (PMID 32720646, 2020). "Indeed, simultaneous ablation of arcuate anorexigenic POMC and orexigenic AgRP/NPY neurons results in mild obesity, suggesting a dominance of POMC neurons in such manipulations." (PMID 31557134, 2020). "Thus, we have described how obesity changes the response of AgRP neurons to food cues, nutrients infusions, and hormone injections, but we cannot measure how the tonic activity of AgRP neurons changes over time." (PMID 32720646, 2020). "Evidence had indicated that any alteration in expression of these orexigenic and anorexigenic peptides (α-MSH and AgRP) may play a potential role in energy homeostasis, food intake and development of obesity." (PMID 32019489, 2020). "Because obesity is associated with complex changes in the neurophysiology of the POMC and AgRP/NPY neurons, the result of ARC neuromodulation by DBS on the PVN in obese patients is tricky and an optogenetic manipulation may be a preferred approach." (PMID 31057350, 2019).
Obesity (continued). "This obesity phenotype, along with increased AgRP expression in the hypothalamus, suggests that Dlx1/2cKO mice may take more food and/or comsume less energy." (PMID 29795232, 2018). "Indeed, while the deletion of LepRb neurons from adult AgRP neurons provokes dramatic obesity, the early developmental deletion of LepRb from AgRP neurons produces little metabolic derangement." (PMID 29914853, 2018). "Important to note, AgRP neuron-specific deletion of GHS-R results in increased energy expenditure, likely due to increased thermogenic function in BAT and subcutaneous WAT, leading to decreased susceptibility to diet-induced obesity." (PMID 28420089, 2017). "Furthermore, we provide evidence that increased mTORC1 signaling in AGRP neurons contributes to diet-induced thermogenesis during early exposure to HF feeding and protects against diet-induced obesity (DIO)." (PMID 28532548, 2017). "We compared ARC gene expression in 8-week-old and 36-week-old Crtc1−/− and WT males, as well as the relative expression of four anorexigenic genes (LepRb, Cart, Nor1, and Glp-r1), three orexigenic genes (AgRP, Npy, and Npy-y1) and the fat-mass-related and obesity-related gene (Fto)." (PMID 29217834, 2017). "Furthermore, sustained elevated NPY/AgRP levels perpetuate a dysfunctional feeding circuit resulting in the development of diet-induced obesity (DIO) from overfeeding." (PMID 27893782, 2016). "Inhibition of PKA by expression of a dominant negative Prkar1a allele in AgRP neurons inhibited hypothalamic CREB phosphorylation in fasted mice and resulted in a lean phenotype and resistance to high-fat diet-induced obesity, partially mimicking the phenotype of the RIIβ KO mouse." (PMID 26381935, 2015). "Alternatively, it is conceivable that the orexigenic capacities of AgRP neurons are negated in states of diet-induced obesity, either because of other neurons increasingly acting as the primary drivers of feeding and body weight or because of changes in neurocircuitry/plasticity." (PMID 26500840, 2015). "We next tested whether Sirt1 overexpression in POMC neurons or AgRP neurons protects mice from diet-induced obesity by feeding them an HFHS diet." (PMID 24374551, 2014). "Thus the usefulness of this drug in treating obesity deserves further exploration, to define the AgRP dependent and independent mechanisms by which TTP2515 exerts its effects on energy balance." (PMID 23762342, 2013). "Selective elimination of LEPRb on either POMC or AgRP neurons produced a mild obesity phenotype." (PMID 23543912, 2013). "Deletion of LepRb specifically from POMC and AgRP neurons in mice lead to mild obesity." (PMID 22276206, 2012). "However, in a previous study pertaining to the regulation of the expression of the hypothalamic MCS by a high fat-diet, we unexpectedly observed an increase in the POMC to AgRP ratio, whilst mice fed this type of regimen exhibited hyperphagia and obesity." (PMID 21544212, 2011). "AGRP is increased in obese men and AGRP levels are correlated with various parameters of obesity." (PMID 19575795, 2009). "In addition, studies have shown that obesity strongly impinges on AgRP neuronal activity dynamics." (PMID 41326798, 2025). "However, whether AgRP neurons, which play a crucial role in energy homeostasis, are involved in age-dependent obesity remains unknown." (PMID 41037185, 2025). "Thus, while multiple studies have shown that obesity alters AgRP neuron responses to food presentation and to gastrointestinal nutrients, these changes are unlikely to be incretin-mediated, as neural responses to incretin receptor agonists remain intact in obese mice." (PMID 40857106, 2025).